IL6 (interleukin 6)
Diseases named in the same sentence as IL6 in open-access papers (continued):
Sharing a sentence is not in itself a finding about the gene and the disease.
Sepsis (continued). "Indeed, in mouse serum, mouse CCR2 protein (the receptor for CCL2) is necessary for expression of mouse IL6 protein that is increased by experimentally induced sepsis in mouse, and IL1 protein increases expression of CCL2 protein." (PMID 21906276, 2011). "In addition, we also found that TNF-α, IL-6, and IL-10 levels were significantly lower in plg-/- mice than in WT mice during sepsis." (PMID 21931850, 2011). "IL-6 is an important player in sepsis-induced muscle atrophy in this model." (PMID 21958504, 2011). "IL-6 is a widely accepted inflammatory parameter in response to major trauma and sepsis." (PMID 21232130, 2011). "In sensitivity analyses, we observed that hazard ratios for the association between IL-6 and 1-year mortality were larger in the subgroup without severe sepsis than among those with severe sepsis." (PMID 21853050, 2011). "IL-6 values above 500 pg/mL were found in patients with sepsis." (PMID 21687569, 2011). "However, serial responses of IL-1β, TNF-α and IL-6 from PBMCs still need to be elucidated in patients with severe sepsis." (PMID 21939530, 2011). "Plasma interleukin-6 and tumour necrosis factor-α concentrations were increased after acid instillation as compared to sepsis, but plasma intercellular adhesion molecule-1 concentration increased during sepsis only." (PMID 22204611, 2011). "Moreover, the IL-6 levels in plg+/- mice were approximately half of those in WT mice at 24 h after induction of sepsis, indicating that the relative levels of plasminogen also affect cytokine production." (PMID 21931850, 2011). "Acid instillation increased IL-6 plasma concentrations as compared to sepsis (P = 0.002)." (PMID 22204611, 2011). "When a multiple linear regression analysis (stepwise method) was used, classified sepsis (r2 = 0.25, P = .003), transferrin (r2 = 0.21, P = .01), IL-6 (r2 = 0.31, P = .002), and the NI (r2 = 0.52, P = .001) were independently associated with the PRISM score (F = 12, P = .0000)." (PMID 20490277, 2010). "The aim of the present study was to investigate the value of thromboelastometry variables as potential biomarkers of sepsis in critically ill adults and to compare these hemostasis-related biomarkers with the established markers procalcitonin, interleukin 6, and C-reactive protein." (PMID 20929576, 2010). "In the septic group, the level of IL-6 decreased significantly within 24 hours after sepsis onset (t0 → t24: P = .021*, t24 → t48: P = .225, t0 → t48: P = .075), but still remained significantly higher than the volunteer group (t24: P < .001***, t48: P < .001***)." (PMID 20847814, 2010). "Increased serum LBP levels have been reported in neonatal early onset sepsis, and is reported to be a better marker in critically ill neonates and children than other markers, such as C-reactive protein, procalcitonin and interleukin-6 (IL-6)." (PMID 20158885, 2010). "However, IL-6 is considered a good independent early marker of postoperative sepsis, severe sepsis and septic shock." (PMID 20230641, 2010). "IL-6 increases at early time points in patients with severe sepsis and septic shock." (PMID 20939898, 2010). "IL-6 is an important pro-inflammatory cytokine and correlates with disease severity in sepsis." (PMID 20482750, 2010). "Measurement of TNF-α and IL-6 at the early phase of sepsis may be helpful to evaluate severity of disease and to estimate outcome." (PMID 22615611, 2010). "Our results therefore suggest that, as in contrast to sepsis, early elevations of IL-6 may play a prominent role in the response to T/HS." (PMID 20027315, 2009). "Thus, in response to sepsis, IL-6 robustly accumulates in the brain and is at least partly produced by the central inflammatory system, although some contribution from the periphery cannot be ruled out." (PMID 19284588, 2009). "Interleukin (IL)-6 produced by enterocytes may have anti-inflammatory and cell-protective effects, and may counteract some of the injurious effects of sepsis and endotoxemia." (PMID 20204057, 2009).
Sepsis (continued). "Thus, we confirmed studies from a murine septic shock model showing that IL-6 predicts outcome in the early phase of sepsis." (PMID 19781105, 2009). "Cipro showed a consistent upregulation of IL-6 production of splenocytes in response to B- or T-cell mitogens, and this may be of benefit in chemotherapy-related sepsis as low Il-6 production from systemic immune compartments correlates with sepsis mortality." (PMID 19401694, 2009). "The sepsis patients in this study had high concentrations of IL-6." (PMID 18925930, 2008). "Previous studies have demonstrated that proinflammatory cytokines play a critical role in the initiation and progression of sepsis syndrome and that TNF-α, IL-1β, and IL-6 are important mediators of hemodynamic, metabolic, and immunologic alterations in the host during sepsis." (PMID 18680601, 2008). "Previous studies have demonstrated that proinflammatory cytokines play a critical role in the initiation and progression of sepsis syndrome and that TNF-α, interleukin (IL)-1β, and IL-6 are important mediators of hemodynamic, metabolic, and immunologic alterations in the host during sepsis." (PMID 18680601, 2008). "Consequently, delayed administration of EGCG did not affect circulating levels of TNF at late stage of sepsis, but specifically attenuated systemic accumulation of HMGB1, as well as IL-6 and KC-two most reliable surrogate markers of lethal sepsis." (PMID 17987129, 2007). "Moreover, IL-6 is the major stimulant in hepaticprotein synthesis, that is, CRP and fibrinogen during acute phase responses.Previous studies have shown that determinations of IL-6 in neonatal blood are ofdiagnostic value in sepsis." (PMID 18274637, 2007). "We compared cytokine concentrations among patients with severe sepsis and septic shock, and observed that concentrations of IL-1β, IL-6, IL-7, IL-8, IL-10, IL-13, IFN-α, MCP-1 and TNF-α were significantly increased in septic shock as compared with severe sepsis." (PMID 17448250, 2007). "The IL-6 -174C allele was associated with an increased incidence of late blood stream infection (BSI) in AA but not Caucasian infants." (PMID 16611358, 2006). "This makes IL-6 an interesting molecule to evaluate in the early phase of infection and sepsis." (PMID 16569262, 2006). "IL-6, LBP and CRP appear to be superior as diagnostic sepsis markers compared with PCT." (PMID 16569262, 2006). "In addition to this, previous studies have shown that correction of hypothermia during sepsis results in decreased IL-6 levels and a significantly increased survival rate." (PMID 17062126, 2006). "In a receiver operating curve analysis of survival of patients with sepsis, the area under the curve (AUC) for MR-proADM was 0.81, which was similar to the AUCs for IL-6, Acute Physiology and Chronic Health Evaluation II score and Simplified Acute Physiology Score II." (PMID 16356231, 2005). "In addition, blockade of IL-6 biological activity following burn injury and/or sepsis has been shown to improve outcome." (PMID 16168063, 2005). "Similarly, during infection and sepsis, insulin resistance is promoted in hepatocytes via interleukin (IL)-1beta, tumor necrosis factor and IL-6 and gluconeogenesis in the liver via a systemic neuroendocrine response, including the release of cortisol, norepinephrine and epinephrine." (PMID 40843859, 2025). "In this study, we hypothesized that the association between blood IL-6 levels and outcomes differs between non-elderly and elderly patients with sepsis." (PMID 39800741, 2025). "Some studies have reported that NETosis is associated with inflammatory biomarkers such as interleukin-6 (IL-6) and procalcitonin (PCT), dysregulated coagulation responses (e.g., increased D-dimer, prolonged prothrombin time, and thrombocytopenia) and tissue damage (e.g LDH) in patients with sepsis." (PMID 41229414, 2025).
Sepsis (continued). "Notably, higher levels of CCL2 and IL-6 in spleen are markers of lethal tularemia, suggesting that the utilization of glutamate might contribute to host sepsis and death." (PMID 40880474, 2025). "From the perspective of pathophysiological mechanisms, HBP and IL-6 are not merely “inflammatory accompanying indicators” but key mediators directly involved in the core pathological process of sepsis, which is the core reason for their accurate association with prognosis." (PMID 41293058, 2025). "In the context of sepsis, a significant elevation in oxidative stress arises primarily from the excessive generation of reactive oxygen species (ROS), a process largely mediated by proinflammatory cytokines such as interleukin-6 (IL-6), interleukin-1 (IL-1), and tumor necrosis factor-alpha (TNF-α)." (PMID 41268545, 2025). "However, clinical trials targeting the well-known mediators associated with the response to sepsis, such as PAMPs, endotoxins, and inflammatory cytokines (e.g., IL-6, IFN-gamma, TNF, IL-1beta) have shown discrete or no efficient results." (PMID 40241761, 2025). "Similarly, lactate though assessing perfusion deficits, remains non-specific for infection source, and although IL-6 is widely used and linked to sepsis severity, it also lacks specificity for distinguishing abdominal from non-abdominal sepsis." (PMID 40510342, 2025). "Specificity of SAE-related biomarkers: while biomarkers like cytokines (e.g., IL-6, TNF-α), S100B protein, and other markers of neuronal injury are elevated in both sepsis and SAE, their levels may be particularly associated with brain dysfunction in sepsis." (PMID 40529149, 2025). "Notably, patients with severe manifestations of SAE, such as coma, exhibit higher plasma concentrations of IL-6 compared to those with milder symptoms like delirium, suggesting a correlation between elevated IL-6 levels and the severity of neurological impairment in sepsis." (PMID 40635709, 2025). "Therefore, an initial measurement of IL-6 in the emergency department could facilitate timely ICU admission for patients with sepsis." (PMID 40142279, 2025). "Notably, there is an inverse relationship between thrombocytopenia and cytokine activation in sepsis, prompting exploration of anti-IL-6 therapies to mitigate inflammation and restore platelet counts since this cytokine is likely a key driver of the cytokine storm in sepsis." (PMID 40003683, 2025). "High values of IL-6 might serve as a good predictor of sepsis mortality." (PMID 40142279, 2025). "Therefore, anti-IL-6 therapy may be considered for critically ill patients who meet all of the following criteria: IL-6 levels ≥ 100 pg/mL, predicted mortality > 40%, concurrent sepsis, and neutropenia." (PMID 41155261, 2025). "Thus, both key TH17-driven cytokines, i.e., TGFβ and IL-6, are activated in patients with sepsis." (PMID 40699834, 2025). "However, combining markers such as PCT, CRP, and IL-6 with clinical judgment and blood culture results may enhance early sepsis detection." (PMID 41011807, 2025). "Both studies, while supporting the diagnostic utility of IL-6, were excluded due to their selective pathogen focus, which introduces threshold and spectrum biases not compatible with pooled estimates intended to reflect sepsis of all etiologies." (PMID 40892314, 2025). "Furthermore, it investigates whether the dynamic changes in IL-6 concentrations over time, i.e., IL-6 kinetics, provide additional prognostic information beyond static baseline measurements, as well as determining their ability to predict sepsis mortality." (PMID 40149943, 2025). "We observed increased values of inflammatory markers in patients with sepsis: the mean value of C-reactive protein was 195 ± 121.90 in group 1 and 98.32 ± 97.96 in group 2—a statistically significant difference (p < 0.0001)—the same results for interleukin 6 (p < 0.0001)." (PMID 40564087, 2025).
Sepsis (continued). "These age-related differences may result in distinct IL-6 kinetics between elderly and non-elderly patients with sepsis, and could lead to different associations between IL-6 levels and clinical outcomes." (PMID 39800741, 2025). "However, since sepsis is the main cause of cytokine storms, it is not valid to infer that the increase in IL-6 levels was due to L. infantum instead of lipopolysaccharide (LPS) from opportunistic bacteria." (PMID 40732663, 2025). "Univariate analysis revealed that RDW (OR=1.947), APACHE II score (OR=2.303), PCT (OR=1.423), IL-6 (OR=1.237), CRP (OR=1.212), cystatin C (OR=1.324), and the main source of infection (OR=1.478) were significantly associated with the development of AKI in children with sepsis." (PMID 41281283, 2025). "Therefore, blocking IL‐6 release and its upstream activation pathways may be a potential strategy for preventing myocardial damage and dysfunction during sepsis." (PMID 39853914, 2025). "However, IL-6+ cells were significantly enriched in infected animals across nearly all cell types and regardless of infection route, and their frequency correlated positively with the sepsis score." (PMID 40178612, 2025). "Moreover, network pharmacology indicated that oxidative stress and inflammation are associated with sepsis-induced ALI; therefore, we detected the expression of oxidative stress factors (MPO, ROS, MDA, and SOD) and inflammatory factors (TNF-α, IL-6, and IL-1β) in LPS-stimulated HUVECs." (PMID 38445620, 2024). "Similarly, a study on sepsis revealed curcumin's ability to decrease serum inflammatory markers (IL-6, IL-18), oxidative stress indicator MDA, and increase antioxidants like Nrf2, catalase, and SOD, implicating its potential to target ferroptosis-related lipid peroxidation in clinical settings." (PMID 38519984, 2024). "Sepsis (sepsis) is a systemic inflammatory response triggered by infection, and its pathologic features include overproduction of peripheral inflammatory factors (e.g., IL-1β, IL-6, TNF-α), which ultimately leads to cytokine storm and multiple organ dysfunction syndrome (MODS)." (PMID 39720715, 2024). "The antibody treatment exerted anti-inflammatory effects via simultaneous inhibition of IL-6, CXCL8/IL-8, CCL3/MIP-1, TNF-α, and IFN-γ production, and had direct and considerable suppressive effects on excessive CCL and CXCL gene expression associated with sepsis immunopathogenesis." (PMID 38177528, 2024). "It has been observed that sepsis-induced endothelial cell activation escalates systemic inflammatory markers such as IL-1β, IL-6, and TNF-α, as well as the production of reactive oxygen species, factors that may accelerate the onset of sepsis-associated delirium (SAD)." (PMID 38357643, 2024). "Specific biomarkers such as C-Reactive Protein (CRP), Procalcitonin (PCT), Interleukin-6 (IL-6), D-dimers, and Fibronectin were included alongside routinely used markers in several studies, highlighting the role of these inflammatory and coagulation markers in sepsis prognosis." (PMID 39767798, 2024). "Moreover, studies have indicated that immunotherapeutic blockade of IL6 could reduce the mortality rate in sepsis." (PMID 39835102, 2024). "Further correlation analysis revealed that MASP-1 expression was significantly positively associated with IL6/JAK/STAT3 signaling and significantly negatively correlated with checkpoint, ferroptosis, HLA, T-cell co-inhibition, T-cell co-stimulation, and necrosis in trauma and sepsis." (PMID 38384415, 2024). "Whether HNF4α regulates IL6-mediated APR in sepsis directly or indirectly requires further study." (PMID 39261648, 2024). "Also, a study reported that a lower IL-6 level was beneficial to sepsis." (PMID 38165570, 2024). "Also, IL-6−/− mice have been shown to increase sepsis severity and mortality in a model of cecal ligation and puncture, which may explain why IL-6−/− + rIL-6 mice evinced comparable high number of cryptococci in blood to IL-6−/− animals at 3-dpi." (PMID 39334365, 2024).
Sepsis (continued). "Although previous literature indicate that the pro-inflammatory response may be impaired in preterm newborns, serum levels of monocyte-derived cytokines, such as TNF-α and IL-6, vary highly between newborns and can reach adult-like concentrations during sepsis." (PMID 38562936, 2024). "Recent studies have shown significant alterations in peripheral cytokines (e.g., IL-1, IL-6) and lymphocyte subpopulations in DLB, but whether these changes indicate immune suppression or are associated with sepsis mortality risk requires further investigation." (PMID 39606027, 2024). "In addition, significant increases in IL-6, IL-8, and sIL-2R were seen in a sepsis." (PMID 39289412, 2024). "This sepsis-induced immunosuppression is typically characterized by dysfunctional monocytes, which show a decreased release of pro-inflammatory cytokines such as tumor necrosis factor α (TNFα), IL-1β and IL-6 upon stimulation with LPS and an enhanced secretion of anti-inflammatory IL-10." (PMID 37759239, 2023). "Thus, the serum levels of TNF-α and IL-6 have been proposed as prognostic parameters for patients suffering septic shock, and immunotherapy using anti-TNF-α or anti-IL-6 monoclonal antibodies, such as afelimomab and tocilizumab, have reduced overall mortality from severe sepsis." (PMID 36675101, 2023). "For example, high serum IL-6 and IL-1 might be biomarkers for sepsis hyper-inflammation, while downregulated HLA-DR and viral reactivation, such as cytomegalovirus, which is the common dormant virus in the human host, possibly indicate sepsis immune exhaustion." (PMID 36982437, 2023). "Although it is currently unclear whether IL-6 inhibition has similar benefits in other cases of sepsis, a recent Mendelian randomization analysis suggests that IL-6 receptor blockade was associated with lower mortality in 11,643 patients of the UK Biobank cohort with non-COVID-19 sepsis." (PMID 38057824, 2023). "However, it has been shown that TNF-α, IL-6, IL-1 and IFN-γ are elevated in sepsis, cancer and other catabolic states, and may jointly cause muscle atrophy by increasing the expression of NF-κB." (PMID 38017491, 2023). "Hence, IL-6 antagonists may be of therapeutic value to prevent the development of severe lung infiltrates and sepsis early and efficiently." (PMID 37733154, 2023). "However, IL-6 clearance was not a risk factor for sepsis in our study; thus, it was not used in developing the prediction model." (PMID 36383295, 2023). "IL-6 may also prove beneficial for midwives in smaller gynecologic clinics lacking neonatology departments, enabling them to assess suspected infections or sepsis in cases where a child exhibits signs of infection." (PMID 38255366, 2023). "IL-6 is amongst the most important in the cytokine network and plays a central role in acute inflammation, human metabolism, and autoimmune cell differentiation and is significant in the evolution of sepsis, especially as an early indicator of the inflammatory state." (PMID 37887780, 2023). "For example, high serum IL-6 and IL-1 might be biomarkers for sepsis-related hyper-inflammation, while down-regulated HLA-DR and viral reactivation (cytomegalovirus; the common dormant virus in the human host) possibly indicate sepsis-related immune exhaustion." (PMID 37373287, 2023). "Finally, BMSC-exos ameliorated the mortality rate, AECII apoptosis, inflammatory cytokine storm including HMGB1 and IL-6, and pathological lung damage in sepsis mice, which also could be prevented by ML385." (PMID 37035447, 2023). "In this context, a non-invasive test for the detection of a promising biomarker, the protein Interleukin-6 (IL-6), could represent a significant advance in the clinical management of cancer, in monitoring the chemotherapy response, or for prompt diagnosis of sepsis." (PMID 37794245, 2023). "However, in this study, IL-2 and IL-4 levels were in normal range, so the increase in IL-6 may be a predictor of KD combined with severe sepsis." (PMID 37234775, 2023).